PRTN3 (proteinase 3)
Diseases named in the same sentence as PRTN3 in open-access papers (continued):
Sharing a sentence is not in itself a finding about the gene and the disease.
ANCA-associated vasculitis (92 papers, 2011 to 2026). "Development of ANCA in ANCA-associated vasculitis is linked with the loss of immunological T-cell and B-cell tolerance to one of two neutrophil proteins: leukocyte proteinase 3 or myeloperoxidase." (PMID 39575034, 2024). "A case of proteinase 3 (PR3)-ANCA-associated vasculitis with MN, in which co-localization of PR3 and IgG along the glomerular capillary walls was observed, was recently reported." (PMID 38892120, 2024). "The presence of ANCA against myeloperoxidase (MPO) and proteinase 3, two proteins in neutrophil granules, is characteristic of ANCA-associated vasculitis." (PMID 35409152, 2022). "These antibodies which are directed against antigens myeloperoxidase-1 (MPO-1) and proteinase-3 (PR-3) are associated with ANCA-associated vasculitis (AAV) which is a type of systemic vasculitis." (PMID 35651411, 2022). "Recently, a complement regulator C4BP was proved to limit the development of LN via inhibition of PRTN3 to significant downregulate neutrophils activity, indicating the possible link between ANCA-associated vasculitis and LN." (PMID 36530895, 2022). "Anti-neutrophil cytoplasmic autoantibodies (ANCA) directed against myeloperoxidase (MPO) and proteinase 3 (PR3) are pathogenic in ANCA-associated vasculitis (AAV)." (PMID 30818380, 2019). "We recently reported that IgA and SIgA antiproteinase 3 (PR3) antibodies are more closely related to disease activity than IgG anti-PR3 in antineutrophil cytoplasmic antibody-associated vasculitis." (PMID 27215344, 2016). "Antineutrophil cytoplasmic antibody-associated vasculitis is described as a group of autoimmune diseases, characterized by the presence of autoantibodies against the neutrophil granule proteins, such as proteinase 3 (PR3) and MPO." (PMID 28123386, 2016). "The C- and P-ANCA in human patients with ANCA-associated vasculitis are mainly directed against proteinase 3 (PR3) and myeloperoxidase (MPO), respectively, and seem to be associated with disease activity." (PMID 25225805, 2014). "Additionally, NET-associated proteases such as neutrophil elastase and proteinase 3 (PR3) can upregulate TF expression, as demonstrated in ANCA-associated vasculitis models." (PMID 40806591, 2025). "Given the good results of rituximab in ANCA-associated vasculitis, especially in proteinase 3–ANCA positive patients, it might be postulated that it would be efficacious in these patients too." (PMID 40225363, 2025). "ANCA-associated vasculitis is a heterogeneous group of rare diseases that present necrotising inflammation of small–medium vessels in conjunction with two major antigens targeted by ANCA for proteinase 3 (PR3) or myeloperoxidase (MPO)." (PMID 38337770, 2024). "PRTN3 encodes proteinase-3, which is another important autoantigens in ANCA-associated vasculitis." (PMID 36530895, 2022). "Both proteinase 3-ANCA (PR3-ANCA) and myeloperoxidase-ANCA (MPO-ANCA) were within normal limits, ruling out ANCA-associated vasculitis." (PMID 40755567, 2025). "ANCA‐associated vasculitis (AAV) is an autoimmune disorder where autoantibodies against neutrophil proteins, particularly MPO and proteinase 3 (PR3), are frequently present." (PMID 41404190, 2025). "For instance, anti-neutrophil cytoplasmic antibodies specific for proteinase 3 (PR3-ANCA) and myeloperoxidase (MPO-ANCA) can induce neutrophil activation, leading to ANCA-associated vasculitis." (PMID 41425580, 2025). "ANCA-associated vasculitis (AAV) is a systemic inflammatory disease of small- and medium-sized vessels, driven by autoantibodies targeting neutrophil proteins such as proteinase 3 (PR3) and myeloperoxidase (MPO)." (PMID 39857611, 2024). "In the literature, eight cases were new-onset ANCA-associated vasculitis, five cases were associated with myeloperoxidase (MPO), and three cases with proteinase 3 (PR3)." (PMID 35632497, 2022).
ANCA-associated vasculitis (continued). "Propylthiouracil (PTU) has been associated with drug-induced ANCA-associated vasculitis (AAV), with antibodies against myeloperoxidase (MPO) and proteinase 3 (PR3) present individually and together having been recognised." (PMID 32703233, 2020). "Expression of KDM6B mRNA is elevated in leukocytes from patients with ANCA-associated vasculitis (AAV) and has been suggested to be the reason for higher proteinase 3 (PR3) mRNA expression in these cells due to derepression of PRTN3 gene transcription." (PMID 27755585, 2016). "Similarly, anti-proteinase 3 (PR3) and anti-myeloperoxidase (MPO) antibodies in individuals with ANCA-associated Vasculitis (AAV) also showed increased Fab glycosylation." (PMID 41301426, 2025). "Finally, although EGPA is classified as ANCA-associated vasculitis (AAV), only ~40% of patients with EGPA test ANCA-positive, with the presence of anti-myeloperoxidase antibodies being more common than anti-proteinase 3 antibodies in serum." (PMID 40630493, 2025). "While c-ANCA or p-ANCA are detected by immunofluorescence, a separate test is needed to detect proteinase 3 (PR3)-ANCA or myeloperoxidase (MPO)-ANCA, and is mandatory for the diagnosis of ANCA-associated vasculitis (AAV)." (PMID 33809645, 2021). "Release of proteinase 3 (PR3) and myeloperoxidase (MPO) may initiate antineutrophil cytoplasmic antibody-associated vasculitis." (PMID 34017259, 2021). "Both local and systemic abundance of PRTN3 found in VSCC patients suggests similarities in the mechanisms underlying VSCC and development of ANCA-associated vasculitis, a group of vasculitides characterized by neutrophil-rich inflammation of small vessels and the presence of circulating ANCAs." (PMID 33374674, 2020). "For instance, histone modifications at the MPO and PRTN3 gene loci may contribute to the pathogenesis of ANCA-associated vasculitis; DNA methylation levels at the PRTN3 promoter can also predict remission and recurrence in ANCA-associated vasculitis." (PMID 41425580, 2025). "ANCA-associated vasculitis (AAV) encompasses a group of multisystem autoimmune diseases characterised by necrotising small-vessel vasculitis and the presence of circulating autoantibodies (ANCAs) directed against the neutrophil cytoplasmic antigens proteinase 3 (PR3) and myeloperoxidase (MPO)." (PMID 36906660, 2023). "ANCA associated vasculitis (AAV) is characterized by the destruction of small and medium-sized arterial vessels, in the presence of circulating autoantibodies toward the cytoplasmic region of the neutrophil (ANCA) predominantly against proteinase-3 (PR3) and myeloperoxidase (MPO)." (PMID 35310798, 2022). "Cases positive for ANCA may demonstrate myeloperoxidase antibody or proteinase-3 (PR3) antibody, both, or neither, and may be termed LAC-induced ANCA-associated vasculitis (AAV)." (PMID 37375793, 2023). "In addition, autoimmune serology was positive for perinuclear ANCA (p-ANCA) (the titer was 128) and negative for cytoplasmic ANCA (c-ANCA) and proteinase 3, according o the clinical manifestations and positive p-ANCA, the diagnosis of ANCA-associated vasculitis (AAV) was considered." (PMID 38287413, 2024).
autoimmune disease (77 papers, 2009 to 2025). A disorder resulting from loss of function or tissue destruction of an organ or multiple organs, arising from humoral or cellular immune responses of the individual to their own tissue constituents. "ANCA vasculitis is an autoimmune disease characterized by pathogenic autoantibodies against MPO or proteinase 3 (PR3)." (PMID 40020049, 2025). "It is considered an autoimmune disease, strongly associated with antineutrophil cytoplasmic autoantibody (ΑNCΑ) directed against leukocyte proteinase 3 (PR3) or myeloperoxidase (MPO)." (PMID 39649240, 2024). "Anti-neutrophil cytoplasmatic antibody (ANCA)-associated vasculitis (AAV) is an autoimmune disease characterized by the presence of autoantibodies directed against myeloperoxidase (MPO) or Proteinase-3 (PR3) expressed by neutrophils." (PMID 31921121, 2019). "ANCA (antineutrophil cytoplasmic antibody)-associated vasculitides (AAV) comprise different types of autoimmune diseases, in which autoantibodies react to proteinase 3 (PR3), or myeloperoxidase (MPO)." (PMID 28077133, 2017). "Anti-neutrophil cytoplasmic autoantibody (ANCA)-associated small-vessel vasculitis is an autoimmune disease characterized by autoantibodies directed against neutrophil granule proteins myeloperoxidase (MPO) or proteinase 3 (PR3)." (PMID 27752292, 2016). "AAV on the other hand, is a rare autoimmune disease of small and medium blood vessels, caused by the loss of tolerance to neutrophil granule proteins proteinase 3 (PR3) or myeloperoxidase (MPO), and is characterised by the presence of anti-PR3 or anti-MPO autoantibodies, respectively." (PMID 37239388, 2023). "Background and aim: Antineutrophil cytoplasmic antibody (ANCA)-associated vasculitis (AAV) is a rare multisystem autoimmune disease developed by autoantibody production against human neutrophilic granulocytes, including proteinase-3 (PR3) and myeloperoxidase (MPO)." (PMID 36552276, 2022). "The serine protease PRTN3 is produced and secreted by granulocytes, and is implicated in endothelial dysfunction during sepsis, while also having roles in organizing immune responses and autoimmune disease." (PMID 36572854, 2022). "Anti-neutrophil cytoplasmic autoantibody (ANCA)-associated vasculitis (AAV) constitute a group of autoimmune diseases characterized by pauci-immune necrotizing small-vessel inflammation and by the production autoantibodies against proteinase 3 (PR3-ANCA) and myeloperoxidase (MPO-ANCA)." (PMID 30356862, 2018). "As the crucial NET components, DNA, histones, elastase, proteinase 3, myeloperoxidase, and LL-37 are the potential sources of autoantigens participating in the flare-up of autoimmune diseases." (PMID 34572313, 2021). "Studies of NETosis in autoimmune disease have suggested a role for proteinase 3 (PR3) in NET induction." (PMID 27708646, 2016). "Anti-neutrophil cytoplasmic antibodies (ANCA) associated small vessel vasculitis are rare but severe autoimmune diseases which share as central pathogenic element the formation of antibodies against myeloperoxidase (MPO-ANCA) and proteinase 3 (PR3-ANCA)." (PMID 27057255, 2014). "Proteinase 3 (PR3) is a potential serum biomarker for this autoimmune disease and is used for routine diagnosis of the disease." (PMID 22438764, 2012). "For instance, systemic lupus erythematosus (SLE) is an autoimmune disease that is characterised by high levels of autoantibodies against proteinase-3 (PR3) and myeloperoxidase (MPO), proteins that are highly expressed and sequestered within neutrophil granules." (PMID 38965211, 2024). "Interestingly, different components of NETs (e.g., double-stranded DNA, histones, citrullinated peptides (CCP), MPO and proteinase 3 (PR3)) are well-described targets of autoantibodies in autoimmune diseases." (PMID 37180120, 2023).
autoimmune disease (continued). "Antineutrophil cytoplasmic antibody (ANCA)-associated vasculitis (AAV) is a rare autoimmune disease (AID) with the hallmarks of chronic inflammation within the blood vessels and the production of ANCAs directed against myeloperoxidase (MPO) and proteinase 3 (PR3)." (PMID 31694209, 2019). "A screen for autoimmune diseases was requested, which was strongly positive for proteinase 3 (PR3) c-ANCA in repeated samples." (PMID 40761967, 2025).
glomerulonephritis (63 papers, 2008 to 2026). A renal disorder characterized by damage in the glomeruli. "These include scleroderma overlap syndromes with associated features of lupus nephritis, myeloperoxidase anti-neutrophil cytoplasmic antibodies (ANCA) or proteinase 3 ANCA-associated glomerulonephritis, or crescentic glomerulonephritis." (PMID 18474117, 2008). "It is characterized by autoantibodies directed against neutrophil proteins myeloperoxidase (MPO) and proteinase-3 (PR3) and is associated clinically with rapidly progressive glomerulonephritis and inflammatory necrosis of small blood vessels in lungs, skin, and other organs." (PMID 31781107, 2019). "The anti-neutrophil cytoplasmic antibody (ANCA) associated vasculitides (AAV) are diseases in which autoimmunity to the neutrophil granule proteins myeloperoxidase (MPO) or proteinase-3 (Pr3) can cause multi-organ injury, including rapidly progressive glomerulonephritis." (PMID 29315316, 2018). "Antineutrophil cytoplasmic antibodies (ANCA) against proteinase 3 (PR3) and/or myeloperoxidase (MPO) together with glomerulonephritis have been associated with various disorders." (PMID 32005179, 2020). "We report a 42-year-old man with subacute infectious endocarditis (IE) with septic pulmonary embolism, presenting rapidly progressive glomerulonephritis and positive proteinase 3-anti-neutrophil cytoplasmic antibody (PR3-ANCA)." (PMID 25506445, 2014). "The two major antigens for ANCA, proteinase 3 (PR3) and myeloperoxidase (MPO), are usually referred to as the serological markers of ANCA-associated vasculitis and glomerulonephritis on ELISA tests, with perinuclear and cytoplasmic lesions in neutrophils, respectively." (PMID 25648906, 2015). "Neutrophil proteases, proteinase-3 (PR3) and elastase play key roles in glomerular endothelial cell (GEC) injury during glomerulonephritis." (PMID 22952809, 2012).
systemic vasculitis (57 papers, 2008 to 2026). "Autoimmune-associated nasal polyps have appeared as part of Wegener’s Granulomatosis (WG), an autoimmune-associated systemic vasculitis associated with proteinase 3 anti-neutrophil cytoplasmic antibodies (PR3-ANCAs)." (PMID 37176151, 2023). "Antineutrophil cytoplasmic antibody (ANCA)-associated vasculitis (AAV) is a group of systemic vasculitis associated with ANCA specific for myeloperosidase (MPO) or proteinase-3 (PR3)." (PMID 24842719, 2014). "The first one is the neutrophil pathway: ANCA bind to membrane-bound myeloperoxidase (MPO) and proteinase-3 (PR-3) molecules of neutrophils, causing them to adhere to the endothelial wall of small vessels and degranulate, resulting mainly in the necrotizing vasculitis component of the disease." (PMID 33817427, 2021). "In granulomatosis with polyangiitis—a small-sized vessel-necrotizing vasculitis associated with giant cell granulomas and necrosis—the hyposialylation of IgG is responsible for the modulation of the pathogenic effects of anti-proteinase 3 (anti-PR3) autoantibodies." (PMID 33810246, 2021). "Additionally, the levels of anti-myeloperoxidase (anti-MPO) and anti-proteinase 3 (anti-PR3) antibodies are useful to diagnose antineutrophil cytoplasmic antibodies associated with systemic vasculitis and related kidney damage." (PMID 30013843, 2018). "Antineutrophil cytoplasmic antibody (ANCA)-associated vasculitides (AAV) are a group of systemic vasculitis characterized by inflammation of small vessels and in most of the cases presence of autoantibodies against neutrophil cytoplasmic antigens (proteinase 3 PR3-ANCA and myeloperoxidase MPO-ANCA)." (PMID 36104505, 2023). "In systemic vasculitis, the intracellular target autoantigens are proteinase-3 (PR3) and myeloperoxidase (MPO), which have signal peptides that allow their association with and storage in secretory vesicles." (PMID 33763057, 2021). "Several types of ANCA can be recognized, but the two subtypes relevant to the onsetof systemic vasculitis are those that are directed towards proteinase-3 (PR3) andmyeloperoxidase." (PMID 29044308, 2017). "As a systemic vasculitis, it targets small- and medium-sized blood vessels and is associated with anti-neutrophil cytoplasmic antibodies (ANCA), particularly those directed against proteinase 3 (PR3)." (PMID 40918843, 2025). "Antineutrophil cytoplasmic antibody (ANCA)-associated vasculitis (AAV) is characterized by necrotizing vasculitis, predominantly affecting small vessels associated with myeloperoxidase (MPO)-ANCA or proteinase 3 (PR3)-ANCA according to the Chapel Hill Consensus Conference." (PMID 29262790, 2017). "In addition, CD177 is pertinent to systemic vasculitis, since one of the principal autoantigens, proteinase 3, is a constituent of primary granules, but is exposed on the neutrophil surface in association with CD177." (PMID 27227454, 2016). "It is characterized by a necrotizing granulomatous inflammation usually involving the upper and lower respiratory tract, a necrotizing vasculitis affecting predominantly small to medium vessels and commonly a necrotizing glomerulonephritis, often in the presence of Proteinase 3 (PR3)-ANCA." (PMID 26137431, 2015). "Two principal antigens on neutrophils—namely, proteinase 3 (PR3) and myeloperoxidase (MPO)—provide epitopes for ANCA binding, promoting endothelial damage and vascular inflammation, culminating in necrotizing vasculitis." (PMID 36834488, 2023). "The disease is characterized by necrotizing vasculitis of small- to medium-sized blood vessels and the presence of anti-neutrophil cytoplasmic antibodies (ANCA) mainly directed against proteinase 3 (PR3)." (PMID 33815414, 2021). "In patients with (primary) systemic vasculitis, ANCA antibodies are usually directed against proteinase 3 (PR3) or myeloperoxidase (MPO)." (PMID 33282799, 2020).
systemic vasculitis (continued). "Anti-neutrophil cytoplasmic antibody (ANCA)-associated vasculitis (AAV) is a rare necrotizing vasculitis with few or no immune deposits, predominantly affecting small vessels associated with ANCA specific for myeloperoxidase (MPO) or proteinase 3 (PR3)." (PMID 30328500, 2018). "The case presented here reports a patient with significant persistent inflammatory arthritis post-vaccination, who was also found to be weakly anti-proteinase 3 antineutrophil cytoplasmic antibody (ANCA-PR3) positive, without evidence of extra-articular systemic vasculitis." (PMID 37038568, 2023). "Autoimmune and systemic vasculitis screenings were negative, including anti-nuclear antibody (ANA), anti-neutrophil cytoplasmic antibody (ANCA) [myeloperoxidase (MPO), proteinase 3 (PR3)], complement levels, cryoglobulins, and antiphospholipid antibodies." (PMID 40765604, 2025).
Arthritis (42 papers, 2010 to 2026). Inflammation of a joint. "The dual blockage of both caspase-1 and proteinase 3 is seen as a potential anti-inflammatory therapeutic option in a murine model of arthritis." (PMID 30583612, 2018). "Indeed, during arthritis-induced sterile inflammation, caspase-1-independent processing of IL-1β leads to disease-associated inflammation as a result of neutrophil recruitment and proteinase 3, while P. aeruginosa infections of the cornea require neutrophil elastase." (PMID 25198773, 2014). "Proteinase 3, a neutrophil protease, cleaves pro-IL-1β near to the caspase-1 binding site to produce an active protein, and inhibiting this protease is protective in a mouse model of arthritis." (PMID 26324708, 2015). "It inhibits proteinase 3, neutrophil elastase, and cathepsin G. These serine proteases are released by joint invading neutrophils following inflammatory stimuli and have shown to be involved in arthritis development." (PMID 21345239, 2011). "Specifically, in models of acute arthritis, proteinase 3 from neutrophils can cleave pro-IL-1β and MAC deposition is known to be elevated in the context of arthritis." (PMID 34650553, 2021).